PIEZO1 (piezo type mechanosensitive ion channel component 1 (Er blood group))
Description:
Pore-forming subunit of the mechanosensitive non-specific cation Piezo channel required for rapidly adapting mechanically activated (MA) currents and has a key role in sensing touch and tactile pain. Piezo channels are homotrimeric three-blade propeller-shaped structures that utilize a cap-motion and plug-and-latch mechanism to gate their ion-conducting pathways. Generates currents characterized by a linear current-voltage relationship that are sensitive to ruthenium red and gadolinium (By similarity). Conductance to monovalent alkali ions is highest for K(+), intermediate for Na(+) and lowest for Li(+). Divalent ions except for Mn(2+) permeate the channel but more slowly than the monovalent ions and they also reduce K(+) currents. Plays a key role in epithelial cell adhesion by maintaining integrin activation through R-Ras recruitment to the ER, most probably in its activated state, and subsequent stimulation of calpain signaling. In inner ear hair cells, PIEZO1/2 subunits may constitute part of the mechanotransducer (MET) non-selective cation channel complex where they may act as pore-forming ion-conducting component in the complex (By similarity). In the kidney, may contribute to the detection of intraluminal pressure changes and to urine flow sensing (By similarity). Acts as a shear-stress sensor that promotes endothelial cell organization and alignment in the direction of blood flow through calpain activation. Plays a key role in blood vessel formation and vascular structure in both development and adult physiology (By similarity). Acts as a sensor of phosphatidylserine (PS) flipping at the plasma membrane and governs morphogenesis of muscle cells (By similarity). In myoblasts, flippase-mediated PS enrichment at the inner leaflet of plasma membrane triggers channel activation and Ca2+ influx followed by Rho GTPases signal transduction, leading to assembly of cortical actomyosin fibers and myotube formation.
Synonyms: Mib; FAM38A; KIAA0233; DHS; ER; LMPH3; LMPHM6
Tractability: Small molecule: a structure with a bound ligand is known. Antibody: UniProt places it where antibodies can reach, with high confidence; UniProt predicts a signal peptide or a membrane-spanning region; its Gene Ontology location is reachable by antibodies, with medium confidence. PROTAC: ubiquitination databases record sites on it; its protein half-life has been measured.
Gene: Protein-coding gene on chromosome 16 (88,715,338 to 88,785,251, reverse strand). Ensembl gene ENSG00000103335.
Subcellular location: Endoplasmic reticulum membrane; Endoplasmic reticulum-Golgi intermediate compartment membrane; Cell membrane; Cell projection, lamellipodium membrane
Pathways (Reactome):
Cellular responses to stimuli: High laminar flow shear stress activates signaling by PIEZO1 and PECAM1:CDH5:KDR in endothelial cells; Mechanical load activates signaling by PIEZO1 and integrins in osteocytes; Turbulent (oscillatory, disturbed) flow shear stress activates signaling by PIEZO1 and integrins in endothelial cells
Gene Ontology:
Molecular function: mechanosensitive monoatomic cation channel activity; protein binding; monoatomic cation channel activity; mechanosensitive monoatomic ion channel activity
Biological process: positive regulation of cell-cell adhesion mediated by integrin; positive regulation of integrin activation; positive regulation of myotube differentiation; cellular response to mechanical stimulus; detection of mechanical stimulus; monoatomic cation transport; regulation of membrane potential; monoatomic cation transmembrane transport; monoatomic ion transmembrane transport
Cellular component: endoplasmic reticulum; endoplasmic reticulum membrane; plasma membrane; cuticular plate; endoplasmic reticulum-Golgi intermediate compartment membrane; stereocilium; lamellipodium membrane; membrane
Genetic constraint (gnomAD): Loss-of-function variants: 278 observed, 262.37 expected, observed/expected ratio (o/e) 1.06, 90% interval 0.96 to 1.17. The synonymous counts are far from expectation, so gnomAD's model fits this gene poorly and the ratio says little. Missense variants: 4,834 observed, 3,268.4 expected, observed/expected ratio (o/e) 1.48, 90% interval 1.44 to 1.51. Synonymous variants: 2,347 observed, 1,445 expected, observed/expected ratio (o/e) 1.62, 90% interval 1.57 to 1.68.
Gene-disease validity (ClinGen):
ClinGen rates the evidence that PIEZO1 causes each of these diseases.
dehydrated hereditary stomatocytosis with or without pseudohyperkalemia and/or perinatal edema (autosomal dominant): Strong.
Homologues: Orthologues: chimpanzee PIEZO1 (99% identical), macaque PIEZO1 (95% identical), dog PIEZO1 (83% identical), mouse Piezo1 (82% identical), rat Piezo1 (82% identical), guinea pig PIEZO1 (82% identical), pig PIEZO1 (80% identical), tropical clawed frog piezo1 (61% identical), zebrafish piezo1 (57% identical), Drosophila melanogaster Piezo (27% identical), Caenorhabditis elegans pezo-1 (25% identical). Paralogues in human: PIEZO2 (47% identical).
Diseases named in the same sentence as PIEZO1 in open-access papers:
PIEZO1 is named in the same sentence as 364 diseases in open-access papers, as found by Europe PMC text mining. Sharing a sentence is not in itself a finding about the gene and the disease. The quoted sentences say what the papers report.
glioma (59 papers, 2019 to 2026). A benign or malignant brain and spinal cord tumor that arises from glial cells (astrocytes, oligodendrocytes, ependymal cells). "In gliomas, high Piezo1 expression is associated with reduced survival time and serves as a strong biomarker for poor prognosis in gliomas." (PMID 38690080, 2024). "This review highlights the biological processes involved with PIEZO1 in CNS cells, with special emphasis on its multiple roles in glioma-associated phenotypes." (PMID 36765838, 2023). "Less malignant isocitrate dehydrogenase‐mutant gliomas typically show lower expression of Piezo1, which is associated with hypermethylation upstream of the Piezo1 promoter." (PMID 37366640, 2023). "We further elaborated the effects of PIEZO1 in gliomas and its underlying mechanisms as well as its clinical application." (PMID 36765838, 2023). "Such a prospective approach is supported by other recent studies emphasising the contribution of PIEZO1 to the development of glioma malignancy and elevated expression of PIEZO1 in peritumoural brain oedema, associated with worse prognoses in glioma patients." (PMID 34390472, 2021). "Piezo1 has been confirmed to be associated with prognosis of several cancers, like breast cancer, glioma, and non-small cell lung cancer." (PMID 32152662, 2020). "To investigate the role of PIEZO1 in gliomas, we analysed PIEZO1 gene expression at the transcriptome level, genomic profiles and the association of PIEZO1 with clinical practice." (PMID 32999349, 2020). "In addition, in gliomas, PIEZO1 expression was also associated with patient age, histopathological subtype, IDH1 mutation status, and chemotherapy." (PMID 40724850, 2025). "The expression of Piezo1 is positively linked to gliomas, and inhibiting the expression of Piezo1 with drugs may be a treatment strategy for gliomas." (PMID 39539343, 2024). "Additionally, the association between Piezo1 expression and the aggressive glioma phenotype is consistent with increasing tissue pressure, and Piezo1 upregulation and function amplify the level and speed of tissue stiffening to aggravate tumor progression." (PMID 39682291, 2024). "High Piezo1 expression causes glioma cells to spread at a faster rate." (PMID 39539343, 2024). "Piezo1 is overexpressed in aggressive human gliomas and it is associated with a poorer prognosis." (PMID 36837670, 2023). "Piezo1 is overexpressed in aggressive human gliomas and is associated with a poorer prognosis." (PMID 36837670, 2023). "Among recent developments, the use of Dooku1 may be an interesting strategy against glioma variants with high expression of PIEZO1." (PMID 34390472, 2021). "To investigate the expression of genes associated with PIEZO1 in the microenvironment in gliomas, we included an ECM-related gene set from the GSEA and found 110 genes that were most relevant to PIEZO1 (Pearson |R|> 0.35) in the CGGA database to draw the heatmap." (PMID 32999349, 2020). "As expression of PIEZO1 is positively associated with gliomas, pharmacological inhibition of PIEZO1 might prove an efficacious strategy in treating these malignant gliomas." (PMID 32999349, 2020). "However, we didn’t find any clinical data describing the association between PIEZO1 expression and glioma." (PMID 32999349, 2020). "Immunostaining and western blot analyses indicated high levels of PIEZO1 in glioma cells in both in vivo and in vitro conditions." (PMID 40791371, 2025). "Piezo1 expression was significantly higher in the IDH1 wild-type group of gliomas than in the IDH1 mutant group and was elevated in the 1p/19q-non-co-deletion group." (PMID 40061015, 2025). "Piezo1 expression was more significantly upregulated in high-grade gliomas (WHO grade III and IV) than in low-grade gliomas (WHO grade II)." (PMID 40061015, 2025).
glioma (continued). "The identification of PIEZO1 as a key mediator in this process suggests new therapeutic opportunities, highlighting the potential for targeting mechanosensitive pathways in glioma and possibly in other cancers." (PMID 40791371, 2025). "Prior work in glioma showed that stiffness-induced PIEZO1 activation triggers integrin–focal adhesion kinase (FAK) signaling, thereby enhancing ECM synthesis and HA deposition in a positive feedback loop that amplifies tissue stiffness." (PMID 41533929, 2025). "We next investigated PIEZO1 activity in glioma cells using electrophysiology techniques to record mechanosensitive ion currents." (PMID 40791371, 2025). "For example, Piezo1 activates integrin-FAK signaling, regulates ECM and reinforces tissue stiffness to promote glioma aggression, while deleting Piezo1 inhibits tumor aggression and prolongs survival." (PMID 38246995, 2024). "GBM, the most aggressive and lethal primary adult brain tumor, showing the highest malignancy among gliomas (IV grade), expresses Piezo1 at the highest level." (PMID 38581527, 2024). "A stiff mechanical environment upregulates Piezo1 expression to further elevate tumor tissue mechanosensation and aggravate glioma progression." (PMID 39539343, 2024). "Piezo1 have been suggested as potential prognostic biomarkers for the early diagnosis of glioma, given the level of Piezo1 is positively correlated with the severity of edema and the degree of compression forces." (PMID 38923822, 2024). "The expression of Piezo1 can result in mechanical stimulation between glioma cells and promote the occurrence and development of tumors." (PMID 39539343, 2024). "Increased intratumoral solid pressure during high-grade glioma formation provides mechanical signals that stimulate Piezo1, which plays an important role in tumor cell proliferation and metastasis." (PMID 39539343, 2024). "How do stiff amyloid plaques in the brains of patients with AD and hard masses in gliomas stimulate the upregulation of Piezo1 expression in astrocytes and microglia, and how does Piezo1 overexpression proliferate in astrocytes and microglia?" (PMID 39539343, 2024). "Previous study has suggested that PIEZO1 is overexpressed in cell membrane, and its expression is negatively correlated with human aggressive glioma patients survival." (PMID 38324181, 2024). "Recent studies have shown that feed-forward circuits mediated by Piezo1 and tumor histomechanics promote glioma growth in CNS." (PMID 39539343, 2024). "Glioma clumps formed by GBM lead to the upregulation of Piezo1 expression, which, in turn, promotes the rapid proliferation and invasion of glioma cells, accelerates the spreading range and speed of the clumps, and creates a vicious cycle." (PMID 39539343, 2024). "A recent study reported that PIEZO promoted glioma tissue stiffening and tumor cell proliferation, which provided a strategy for targeting PIEZO1 to break the disease-aggravating feedforward circuit." (PMID 38324181, 2024). "Upregulated PIEZO1 is associated with worse overall survival outcomes and higher WHO grades in glioma patients." (PMID 38398074, 2024). "The expression of Piezo1 is significantly higher in GBM than in lower-grade gliomas (WHO grades II and III)." (PMID 39539343, 2024). "In gliomas, Piezo1 expression has been shown to correlate closely with the tumor malignancy grade and inversely with patients’ survival." (PMID 38581527, 2024). "In a Piezo1-dependent manner, glioma cells interact with aberrant glioma tissue mechanics to promote malignancy." (PMID 38267432, 2024). "When Piezo1 is overexpressed, glioma cells exhibit a high degree of activity, leading to rapid proliferation and invasion." (PMID 39539343, 2024). "The elevated Piezo1 localizing at focal adhesions of the glioma processes enhances Ca2+ influx, which promotes glioma invasion by triggering the integrin‐FAK signaling." (PMID 38923822, 2024).
glioma (continued). "Enhanced stiffness between glioma cells and the tumor microenvironment regulates Piezo1 activation and promotes pathological processes." (PMID 39539343, 2024). "For invasive human glioma, Piezo1 is overexpressed to activate integrin FAK signaling and promote tumor invasiveness." (PMID 38690080, 2024). "Previous studies have shown that Piezo1 is highly expressed in glioma, and its expression is negatively correlated with patient survival." (PMID 39539343, 2024). "Glioma molecular subtypes and clinical manifestations are highly compatible with Piezo1 expression, as glioma is one of the most prevalent primary malignancies in the adult CNS." (PMID 39539343, 2024). "It has been shown that the high tissue pressure generated by high-grade glioma provides mechanical stimuli for the Piezo1 channel." (PMID 36837670, 2023). "In glioma, Chen and colleagues have shown that Piezo1 can trigger glioma aggressiveness in D. melanogaster." (PMID 37762011, 2023). "Strikingly, PIEZO1 physically localizes to the focal adhesion of glioma cells, catalyzing the maturation and growth of the focal adhesion through a force-dependent calcium signaling pathway." (PMID 36765838, 2023). "Based on the existing advanced studies, we propose the promising potential of PIEZO1 in the treatment of neurological diseases, especially gliomas." (PMID 36765838, 2023). "Overall, PIEZO1 can be used as an indicator of glioma malignancy and is able to predict the clinical outcome in patients with gliomas." (PMID 36765838, 2023). "PIEZO1 is overexpressed in aggressive human gliomas, and its expression inversely correlates with patient survival." (PMID 36768856, 2023). "In brain tumor cells, tissue stiffening promoted Piezo1 overexpression, that increased glioma aggression through Piezo1 mediated ion conductance." (PMID 37293127, 2023). "Clinical studies on the expression of PIEZO1 in patients with gliomas demonstrate a similar tendency." (PMID 36765838, 2023). "Piezo1 specifically is overexpressed in aggressive human gliomas, and its expression is inversely correlated with the patient’s prognosis." (PMID 37895420, 2023). "On the other hand, as a therapeutic target in gliomas, PIEZO1 acts as an ion channel for translating mechanical stimuli to electrical and chemical signals." (PMID 36765838, 2023). "In response to high ECM stiffness, glioma cells activate Piezo1 at focal adhesion sites and increase calcium influx, which activates integrin-FAK signaling and reinforces ECM stiffening." (PMID 37864030, 2023). "Piezo1 is important in transmitting increased matrix stiffness to resident cells to modulate cell behavior, for example in Alzheimer’s disease, glioma and the ageing brain." (PMID 37752116, 2023). "A large RNAseq study of 1633 glioma samples determined that PIEZO1 expression was highly correlated with malignant GBM and poor survival outcomes." (PMID 36768856, 2023). "On one hand, during glioma genesis, PIEZO1 gathers around focal adhesions, which activates regional calcium fluctuations and leads to adhesion maturation and cell polarization." (PMID 36765838, 2023). "As a result, the harsher environment increases the expression of Piezo1, which enhances the mechanosensory capacity of cancer cells and promotes glioma aggressiveness." (PMID 37895420, 2023). "In short, an increased expression of PIEZO1 in most aggressive tumors, including glioblastoma, indicates a mechanical sensing and growth advantage of glioma cells." (PMID 36765838, 2023). "Both bioinformatics and clinical data showed that Piezo1 expression was upregulated in all histological subtypes of glioma, from LGG to GBM, and that its expression was positively correlated with malignancy." (PMID 37366640, 2023). "Intriguingly, studies have indicated that PIEZO1 can enhance aggressiveness in glioma by modulating tissue mechanics." (PMID 37983931, 2023).